IL6 (interleukin 6)
Diseases named in the same sentence as IL6 in open-access papers (continued):
Sharing a sentence is not in itself a finding about the gene and the disease.
diabetic nephropathy (continued). "In this respect, two recent publications using the same cohort showed that patients treated with SGLT-2i have lower levels of IL-6, with a mechanism of action network model identifying IL-6 as a SGLT-2i-sensitive, central hub in the development and progression of diabetic nephropathy." (PMID 35503137, 2022). "Serum markers such as IL-6 and MCP-1 are significantly altered in the early stages of kidney injury, and the detection of relevant molecular markers in peripheral blood provides a novel auxiliary reference for the clinical management of diabetic nephropathy." (PMID 35756496, 2022). "In the present study, the significantly higher IL-6, MCP-1, and NF-κB levels in the research group than in the observation group suggest the involvement of IL-6, MCP-1, and NF-κB in the progression of diabetic nephropathy, which was consistent with the results of the previous research." (PMID 35756496, 2022). "The nephroprotection of fucoidan nanoparticles appears to be related to the antioxidative stress that suppresses MDA and increases SOD and GPx expression and the anti-inflammatory effect that decreases IL-6 and TNF-α, which can further decrease BUN and creatinine levels in diabetic nephropathy." (PMID 35685736, 2022). "Previous studies revealed that 6-shogaol ameliorated diabetic nephropathy in db/db mice partly through its anti-inflammatory action by decreasing the TNF-α, monocyte chemotactic protein-1 (MCP-1), and IL-6 levels in the circulation and kidneys while suppressing NF-κB expression." (PMID 36355111, 2022). "In addition, apigenin-solid lipid nanoparticles (SLNPs) to reduce renal mRNA expression levels of IL-6, TNF-α, and IL-1β in streptozotocin-induced diabetic nephropathy rats." (PMID 36422572, 2022). "In a study involving hemodialysis patients with diabetic kidney disease, the activity of the antioxidant enzymes catalase (CAT), superoxide dismutase (SOD), and glutathione peroxidase (GSH-Px) was assessed, and IL-6 and TNF-α levels were determined as an indicator of oxidative stress." (PMID 36615736, 2022). "Diabetic patients with diabetic nephropathy have higher serum IL-6 levels than those without diabetic nephropathy, and IL-6 participates in the pathogenesis and progression of diabetic nephropathy." (PMID 34425760, 2021). "Also, inflammatory such as IL-6 and TNF-α are significantly correlated with HbA1c and diabetic nephropathy." (PMID 34917685, 2021). "INHBC may also induce the secretion of IL-6 and TGF-β and promote the proliferation and inhibit the apoptosis of renal cells during diabetic nephropathy." (PMID 34641864, 2021). "In addition, also OPG-induced IL-6 upregulation and oxidative stress show that OPG can directly damage the kidney, as it has been shown that IL-6 expression increases in diabetic nephropathy, and that oxidative stress induces fibrogenesis in CKD." (PMID 28683789, 2017). "In addition, SGLT2is have been shown to reduce circulating levels of interleukin 6 (IL-6), tumor necrosis factor 1 (TNF-1) receptor, and matrix metalloproteinase-7 (MMP-7) and fibronectin-1, key molecules in the formation process of diabetic kidney disease." (PMID 41007686, 2025). "Moreover, vitamin D is essential for protecting kidney function through reducing 24 h urine protein and inflammatory status (CRP, TNF- α, IL-6) in patients with diabetic nephropathy, but without effects on eGFR." (PMID 36900141, 2023).
diabetic nephropathy (continued). "The AUCs of IL-6, MCP-1, and NF-κB for predicting the prognosis of patients with diabetic nephropathy were 0.562, 0.634, and 0.647, respectively, and the AUC of the three combined detection for predicting the prognosis of patients with diabetic nephropathy was 0.889." (PMID 35756496, 2022). "This pathway may implicate inflammatory biomarkers with shorter half-life, such as interleukin-6, TGF-β, and TNF-α, because studies have shown that Tocovid reduced serum creatinine and ameliorated diabetic nephropathy through downregulation of TGF-β and TNF-α in diabetic rats." (PMID 30227659, 2018). "In a rodent model of DM and diabetic nephropathy, MSC treatment ameliorated diabetic nephropathy via inhibition of MCP-1 expression by secreting HCP, thus reducing macrophage infiltration and down-regulating Il-1β, IL-6, and TNF-α expression in the renal tissue of diabetic rates." (PMID 24936198, 2014). "A lack of association between IL6 G-174C or IL1 RA genotypes and significant association between CRP and diabetic nephropathy has been reported earlier too, indicating that elevated CRP levels are associated with diabetic nephropathy independent of polymorphisms in cytokine genes." (PMID 19357773, 2009).
lung disease (153 papers, 2005 to 2026). "Post-treatment impaired pulmonary function, lymph node metastasis, prior lung disease, and elevated preoperative interleukin-6 levels are risk factors for postoperative pulmonary complications." (PMID 41100188, 2025). "Our identification of post-treatment impaired pulmonary function, prior lung disease, lymph node metastasis, and elevated preoperative IL-6 levels as risk factors for PPCs shares similarities with existing literature." (PMID 41100188, 2025). "Our research has shown that, in SLE patients, elevated serum IL-6 levels (>1.53 pg/mL) are associated with an increased risk of constitutional symptoms (fever), lung disease, and cardiovascular changes." (PMID 37371554, 2023). "There is increasing evidence indicating that IL-6 is an early biomarker of lung damage and is closely associated with prolonged mechanical ventilation, increased morbidity, and mortality in lung diseases." (PMID 38249419, 2023). "Both TNF-a and IL-6 have been shown to be independent risk factors of increased morbidity and mortality in hypoxic lung disease, particularly in COPD." (PMID 35634304, 2022). "The systemic concentration of IL-6 is elevated in patients with lung disorders, and IL-6 is associated with the apoptosis of cells in pulmonary tissue." (PMID 34220536, 2021). "In particular, we observed a significant increase of the U/S NEFA ratio that was associated with salivary IL-6 levels, as well with lung disease severity in CF patients." (PMID 33171650, 2020). "The inflammatory mediators implicated in lung disease, including C-reactive protein, fibrinogen, activated complement components, and cytokines (e.g., interleukin 6, interleukin 1, tumor necrosis factor-α) have also been associated with the development of AF." (PMID 23118762, 2012). "Together, these studies demonstrate adenosine dependent expression of IL-6 during chronic stages of pulmonary disease in the ADA-deficient model." (PMID 21799929, 2011). "Furthermore, post-treatment impaired pulmonary function, prior lung disease, lymph node metastasis, and elevated preoperative IL-6 levels were risk factors for PPCs." (PMID 41100188, 2025). "Indeed, treatment with IL-1 or IL-6 inhibitors was demonstrated as a risk factor in the development of sJIA lung disease." (PMID 33777039, 2021). "IL‐6 has also been implicated in the pathophysiology of pulmonary diseases." (PMID 33523477, 2021). "Moreover, MMP9, which has been implicated in the pathogenesis of several lung diseases and injury, has been shown to increase the expression of IL-6 in response to O3." (PMID 33260937, 2020). "As we, further, identified the levels of Il17 and Il6 in the bronchoalveolar lavage, a clinically accessible tissue, to be associated with severe lung disease this pathway may have potential for both diagnostic and therapeutic intervention." (PMID 28912510, 2017). "Interestingly different gene combinations were associated with the less severe (IL-6; Pmd) or more severe form (IL-10; Pad) of pulmonary disease." (PMID 22140472, 2011). "In pulmonary diseases, particularly in inflammation associated with OSAHS, IL-6 promotes inflammatory and tissue damage responses." (PMID 40129771, 2025). "IL-6 intensifies the progression of pulmonary diseases by activating immune cells in the lungs and promoting the release of inflammatory cytokines." (PMID 40129771, 2025). "Currently, IL-6 is used as a prognostic marker in several diseases, including cancer, cardiovascular disease, and lung disease." (PMID 40278353, 2025). "Elevated levels of interleukins (IL-6, IL-8, and IL-12) have been documented in cases of pulmonary diseases and vascular remodeling." (PMID 40149646, 2025). "In those with advanced CF lung disease (n=14), 3 months of ETI treatment reduced plasma IL-6 levels alongside associated reductions in the acute phase proteins C-reactive protein and α1 anti-trypsin, changes that were also apparent at 1 year." (PMID 39687397, 2024).
lung disease (continued). "In the patients with severe lung disease, higher nasal IL-6 and IL-8 levels were correlated with better lung function and high NE was correlated with better CT scores." (PMID 39456863, 2024). "Previous reports have suggested the potentially crucial role of IL-6 produced by macrophages in fibrotic progression and lung disease." (PMID 37403021, 2023). "IL-6 is a pro-inflammatory cytokine extensively studied in COPD and pulmonary diseases and associated with a worse prognosis." (PMID 36836801, 2023). "The proinflammatory and profibrotic cytokine interleukin-6 (IL-6) is associated with the signalling of adenosine via A2BAR and also plays a pivotal role in these pulmonary disorders." (PMID 37569749, 2023). "Some of them were found previously, for example, the presence of previous comorbidities, especially pulmonary diseases, high levels of ferritin, or IL-6 levels." (PMID 37311004, 2023). "The JAK/STAT pathway is activated by a variety of pro-inflammatory cytokines, such as IL-6, IL-11, and IL-13, which are upregulated in different lung diseases." (PMID 36793900, 2023). "IL-6 is a well-known biomarker of inflammation and metabolic dysfunction and has been suggested to be a predictor of lung disease severity." (PMID 36615108, 2022). "High levels of IL-6 and TNF-α have been associated with worse prognosis and higher mortality rate in patients with lung disease." (PMID 35745755, 2022). "Perhaps more importantly, patients with severe lung disease had more peripheral IL-6+ B cells compared to patients with mild disease, and patients with diffuse SSc had more IL-6+ B cells compared to patients with limited SSc." (PMID 35860745, 2022). "Our data have shown, that from all analyzed pro-inflammatory cytokine genes, onlyIL1B, but notTNF, CXCL8, IL6, orIL10 clearly play a crucial role in CF manifestation, determining the severe character of lung disease." (PMID 39185143, 2022). "Among these cytokines, IL-6 seems to be a crucial factor in exacerbating pulmonary disease and severity in COVID patients." (PMID 35812188, 2022). "Among these, IL-5, IL-17, IL-13, IL-23, and IL-6 are pro-inflammatory cytokines upregulated in patients with pulmonary diseases." (PMID 35806353, 2022). "Our data also indicate that increased cf-MtDNA copy numbers was significantly associated with expression of inflammatory cytokines, especially IL-6, which served to aggravate pathogenesis of the two lung diseases." (PMID 34181353, 2021). "DTL cytokines which correlated significantly with the degree of lung disease (OI) included IL-1RA (r = 0.54), IL-6 (r = 0.53), IP-10 (r = 0.67), LIF (r = 0.52), MCP-1 (r = 0.66) and SDF-1α (r = 0.52)." (PMID 34239039, 2021). "In patients, the clinical phenotype and severity of lung disease, coincidend with the introduction of IL-1 and IL-6-targetting biologics (and decreasing used of corticosteroids), suggesting potential contribution of drug exposure." (PMID 33777039, 2021). "IL‐6 is a pleiotropic cytokine involved in mediating the progression of a number of lung diseases, including COPD." (PMID 34323408, 2021). "It was reported that IL6 gene (MIM:147620) plays an active role in pathogenesis of lung disease like asthma." (PMID 32802897, 2020). "Previous studies have shown that miR-223-3p can directly bind the 3′ UTR of Il6 and inhibit its expression during inflammatory responses after liver and lung diseases." (PMID 32493731, 2020). "Many of these occupational lung diseases are mediated by proinflammatory cytokines including interleukin-6 (IL-6) and IL-8, whose levels are known to increase in respiratory cells and tissues following swine dust exposure." (PMID 31481850, 2019). "IL-6 and epiregulin are associated with a several CID, such as cancer, asthma and other pulmonary diseases, and Crohn’s disease." (PMID 31159449, 2019).
lung disease (continued). "IL-6 has been shown to play a pivotal role in the pathogenesis of lung diseases and to act as a key modulator of overall immune response, as well as non-immune cell responses." (PMID 31159449, 2019). "The inflammatory cytokine IL-6 has been shown to be elevated in different lung diseases and is closely related to COPD." (PMID 31275415, 2019). "Apart from neutrophils, the other innate and adaptive immune cells also contribute to the pathophysiology of CF-lung disease by elevating levels of several pro-inflammatory cytokines and chemokines such as IL-1β, IL-6, IL-8, TNFα, IL-33 and IL-17." (PMID 29301535, 2018). "The progression of lung disease was monitored by quantifying changes in inflammatory markers (NFκB), cytokines (IL-6/IL-10), neutrophil activity (MPO, myeloperoxidase and/or NIMP-R14) and T-reg numbers." (PMID 29301535, 2018). "Many studies had revealed that the proinflammatory factory like TNF-a, IL-1a and IL-6 have an effect on the lung disease." (PMID 28521806, 2017). "Cytokines such as TNF-alpha, IL-6, and IL-10, modulate the recruitment and the activation of leukocytes in lung diseases." (PMID 26569396, 2015). "These are the first studies to demonstrate the ability to halt the progression of fibrosis using IL-6 neutralizing antibodies suggesting IL-6 as a potential therapeutic target for treating pulmonary disorders where fibrosis is abundant." (PMID 21799929, 2011). "Understanding the mechanisms and timing behind the protective and remodeling activities of IL-6 in various lung disorders will be important if IL-6 blocking strategies are to be pursued for the treatment of these disorders." (PMID 21799929, 2011). "Understanding the cellular source and mechanism of IL-6 production in specific lung disorders will be essential to deciphering the effects of A2BR based therapies." (PMID 21799929, 2011). "Alveolar and interstitial scores on HRCT and IL-6 plasma levels were also assessed as lung disease activity indices." (PMID 16107215, 2005). "In addition, tumor necrosis factor-alpha (TNF alpha) and interleukin-6 (IL-6) affected the progression of lung diseases." (PMID 40242447, 2025). "The variables selected by LASSO regression included age, smoking history, prior pulmonary disease, adverse events during neoadjuvant chemoimmunotherapy, post-treatment impaired pulmonary function, lymph node metastasis, and preoperative interleukin-6 (IL-6) elevation." (PMID 41100188, 2025). "IL-6, a key mediator of fever and acute-phase responses, has been shown to rise in conditions of environmental stress and contribute to the pathogenesis of cardiovascular and pulmonary diseases." (PMID 38920561, 2024). "Il6 is widely recognized as a significant mediator of inflammation in various lung diseases." (PMID 38254192, 2024). "Its impact on HLFs goes beyond MIF, including the stimulation of COX-2, IL-6, and MMP-2 expression, along with the synthesis of PGE2 implicated in inflammation and remodeling of the ECM, processes that play significant pathogenetic roles in lung diseases." (PMID 38145300, 2024). "Our data suggest that IL-6 deficiency causes early inflammation but does not alter pulmonary disease as the infection progresses." (PMID 39334365, 2024). "Therefore, the balance of Treg and Th17 cells can be regulated by adjusting the expression of cytokines such as IL-17A, IL-6, IL-23, IL-33 and Foxp3 to achieve the goal of treating lung diseases." (PMID 37795866, 2023). "However, in CF lung disease, there is an elevation in pro-inflammatory cytokines such as IL-6, IL-8, tumor necrosis factor-α and IL-1β, along with a decrease in anti-inflammatory cytokine IL-10 and anti-inflammatory mediator lipoxin levels." (PMID 37795866, 2023). "However, IL-6 levels in the sputum of patients with advanced CF lung disease was extremely low but normal systemic IL-6 production was found." (PMID 35139898, 2022).